ASS1 (argininosuccinate synthase 1)
Diseases named in the same sentence as ASS1 in open-access papers (continued):
Sharing a sentence is not in itself a finding about the gene and the disease.
tumor (continued). "The presence of enzymes involved in arginine biosynthesis, like argininosuccinate synthase (ASS1) and argininosuccinate lyase (ASL), plays a crucial role in determining a tumor’s arginine auxotrophy." (PMID 39590860, 2024). "Intriguingly, FOXO3a levels inversely correlated with ASS1 and ASL across tumor stages, indicating differential regulation by FOXO3a." (PMID 39090094, 2024). "Before using ADI-PEG20, we should first determine whether it is an ASS1-deficient tumor or not." (PMID 38053661, 2023). "On the one hand, both ASS1, which is the key enzyme in arginine metabolism, and PYCR1, which is responsible for proline synthesis, were highly expressed in both tumour tissues and cell lines under limited oxygen conditions." (PMID 36978187, 2023). "Correspondingly, ASS1, ALDH18A1 and PYCR, which regulate the synthesis of arginine and proline, also showed up-regulated expression in tumor and lymphoid tissues (Fig. 3a5, a6, a10, b3–b5)." (PMID 37164975, 2023). "In their findings, AR expression was negatively correlated with ASS1 expression, thus contributing to RCC tumor progression." (PMID 36430837, 2022). "In vivo, Arginine is synthesized from aspartate or citrulline through argininosuccinate synthetase (ASS1) and argininosuccinate lyase (ASL), which act as key regulators in determining the arginine-dependency of tumor cells." (PMID 35178349, 2022). "Among them, the correlation between the CRIP2 protein and mesenteric diseases is strongest, and the abundance of other three proteins (STXVP2, ASS1, and CBD) is related to the heterogeneity of tumor location." (PMID 36091379, 2022). "In our earlier studies, we demonstrated that 30% of GBM lack the expression of ASS1 and depleting arginine using pegylated arginine deiminase (ADI-PEG20) resulted in cell death in vitro and tumor regression in an orthotopic xenograft model." (PMID 35113813, 2022). "However, there is evidence that ASS1 may act as a tumor suppressor gene." (PMID 35898872, 2022). "ASS1, regulated by ATF4 and CEBPβ in tumor cells, is increased to enhance the synthesis of arginine from citrulline." (PMID 36231064, 2022). "Under glucose deprivation, ASS1 expression is induced by c-MYC, therefore promoting tumor cell survival by upregulating NO production and activating the gluconeogenic enzymes via S-nitrosylation." (PMID 35910381, 2022). "In this study, we examined the expression of two major enzymes involved in arginine depletion and replenishment in the tumor microenvironment, namely ARG2 and ASS1, respectively, in a series of non-small-cell lung carcinomas (NSCLC)." (PMID 34344457, 2021). "Although most HCC samples exhibited low ASS1 expression, Korean HCC patients with increased ASS1 expression in their tumor tissue have a more favorable prognosis than those with lower expression levels." (PMID 33838671, 2021). "Studies of tumor tissue from Korean HCC patients showed that, although ASS1 expression was low in most samples, high levels of ASS1 were associated with favorable overall survival of patients." (PMID 33838671, 2021). "Our results showed that the C13-C14 double bond in SPA and LM-2I was essential for the binding of ASS1 to SPA and LM-2I, and the tumor inhibitory effect of SPAH was significantly reduced as compared with SPA." (PMID 33859183, 2021). "Consistently, all the six DEGs (GLS2, ASS1, FOLH1B, AGXT2, CPS1, and GPT2) enriched in “arginine biosynthesis” in our results were significantly downregulated in tumor hepatic tissue from HBV-infected patients compared with adjacent nontumor tissues." (PMID 32775402, 2020). "To assess the clinical importance of ASS1 expression in PDAC, we evaluated ASS1 protein levels in 138 patient tumor samples on a well-annotated PDAC tissue microarray by immunohistochemistry." (PMID 31903153, 2020). "Among the remaining 11 cases, 2 tumor samples were ASS1−OTC− and 9 were ASS1+OTC−, all would be expected responders due to their low-endogenous ASS1/OTC expression." (PMID 30808864, 2019).
tumor (continued). "Nevertheless, these findings are consistent with the conclusion that AR expression is negatively correlated with ASS1 expression, thus contributing to RCC tumor progression, likely by regulating the ceRNA activity of ASS1 pseudogenes." (PMID 31000693, 2019). "Among the eight down-regulated genes, one is an oncogene (NEAT1), six are tumor-suppressor genes (ASS1, PTPRD, ISG15, TGFBI, SELENBP1, MEG3) and one gene serves as both an oncogene and tumor-suppressor gene (CDH17)." (PMID 30563222, 2018). "The amount of nitrotyrosine signal was variable in vehicle and ADI-PEG20-treated tumours, but ADI-PEG20 clearly reduced overall nitrotyrosine signal, confirming inhibition of NO-production in ASS1-proficient tumours in vivo." (PMID 26972697, 2016). "We used the ASS1-positive HCT116 colon-carcinoma cell line, well established for forming hypoxic tumours, as a model to assess the effects of combining arginine-deprivation with hypoxia." (PMID 26972697, 2016). "TCGA-A tumours showed higher expression of most group I/FTEC epithelial proteins such as KRT7, MSLN, CDH6, ASS1 and EPCAM, while TCGA-B tumours had higher expression of the group III/IOSE mesenchymal proteins ITGA5, HMOX1, SMTN and GJA1 (refs 7, 34)." (PMID 27561551, 2016). "We show for the first time an inhibitory effect of ADI-PEG20 on hypoxia-signalling, ASS1 and hypoxia-induced NO in tumours; ADI-PEG20 inhibited proliferation and expression of HIF-α, iNOS, ASS1, VEGF and GLUT-1 protein." (PMID 26972697, 2016). "Immunohistochemistry (IHC) staining showed that while the UCEs CPS1, ASS1, ASL, and ARG1 were highly expressed in the periportal (zone 1) and midzonal areas (zone 2) in healthy control mice, they were expressed at various levels in the end-stage tumor tissues." (PMID 41512056, 2026). "Interestingly, we also observed a heterogeneous distribution of argininosuccinate even if ASS1 and ASL were overall suppressed in these tumours." (PMID 41213938, 2025). "Addressing the dysregulation of enzymes such as CPS1, ASS1, ARG1 and OTC could offer new strategies to curb HCC progression by manipulating the tumor’s metabolic dependencies." (PMID 40025169, 2025). "This oxidative damage can lead to apoptosis or necrosis of tumor cells, which en-hances the therapeutic effect of radiotherapy, independent of ASS1 expression." (PMID 39239650, 2024). "Levels of argininosuccinate synthetase 1 (ASS1) and argininosuccinate lyase (ASL), key enzymes in arginine metabolism, were increased in primary ESCC tumors but decreased in lymph-metastatic tumor tissues." (PMID 39090094, 2024). "In tumour cells that do not express ASS1, promoting the degradation of extracellular arginine triggers apoptosis." (PMID 39051546, 2024). "We confirmed iNKT cells within the EG7 tumour microenvironment express ASS1, regardless of αGalCer treatment." (PMID 35962843, 2023). "To identify which tumor-dependent pathways related to macrophage signaling, we analyzed the gene expression profile of the three ASS1-negative MPM cell lines (2591, MSTO and JU77) treated with ADI-PEG20." (PMID 37010783, 2023). "Tumoral downregulation of ASS1 confers tumor cells to be more dependent on extracellular arginine since ASS1-negative cells fail to mediate arginine biosynthesis for tumor survival." (PMID 35910381, 2022). "Sufficient tumour DNA at baseline was available for one patient only revealing modest methylation at the ASS1 promoter (0.46, data not shown)." (PMID 35466524, 2022). "Our study provides compelling evidence that arginine deprivation combined with IR is a promising immunotherapeutic strategy for the treatment of ASS1+ GBM, which operates by enhancing the production of cytotoxic levels of peroxynitrite and selectively modulating GAMM to become tumor attacking." (PMID 35113813, 2022).
tumor (continued). "The arginine succinate synthetase 1 (ASS1) is an arginine (Arg) biosynthesis process (key enzyme in HIF-1) that controls the silencing of ASS1 and starves Arg, thereby inhibiting the growth of Arg vegetative tumor cells." (PMID 35953907, 2022). "The mechanism of ASS1 downregulation, even though not fully elucidated, is undoubtedly beneficial for tumors if ASS1 acts as a tumor suppressor gene." (PMID 35898872, 2022). "ADI-PEG20 can disrupt pyrimidine pools in ASS1-lacked high-grade gliomas to increase tumor sensitivity to the antifolate and pemetrexed." (PMID 35910381, 2022). "CEACAM5 and HMGB3 showed significant differences in expression between the two groups, and PLAU and ASS1 showed slightly higher expression in tumor tissues, but the difference was not statistically significant." (PMID 36397035, 2022). "However, ASS1 in T cells is still poorly expressed because of the tight chromosome that cannot bind to ATF4 and CEBPβ, resulting in impaired T-cell anti-tumor immunity." (PMID 36231064, 2022). "Decreased levels of NO metabolites and nitric oxide synthase expression have been observed in renal cellular carcinomas and tumor cells lacking ASS1 and ASL." (PMID 35910381, 2022). "In the present study, we demonstrate that arginine deprivation using ADI-PEG20 favorably alters the immune microenvironment of ASS1-positive GBM tumors and in combination with ionizing radiation (IR) leads to complete tumor elimination with a highly significant increase in survival." (PMID 35113813, 2022). "We concluded that like ARG2 and ASS1, ASL can serve as a metabolic tumor suppressor in ccRCC." (PMID 34861885, 2021). "Analysis of the extent of expression in the tumor stroma CAFs showed that no ASS1 expression occurred in the vast majority of tumors, thus 93/98 cases (negative 94.8%), while expression in 10–40% of the area of the stroma was noted in 5/98 (5.2%) cases." (PMID 34344457, 2021). "However, this analysis also revealed that ASS1 and NOS are markedly downregulated in tumour tissue compared to normal brain." (PMID 33809510, 2021). "Due to the lack of key argininosuccinate synthetase 1 (ASS1), some tumor cells cannot synthesize arginine by themselves." (PMID 34858835, 2021). "ASS1 downregulation was also detected in the U251 GBM cell line when exposed to NS culture, thus recapitulating the results from NCH644 and human GBM tumours." (PMID 33809510, 2021). "Western analysis of tumor tissue showed that treatment with cisplatin plus decitabine increased levels of cleaved PARP relative to cisplatin alone and administration of decitabine induced upregulation of ASS1 in HCC-implanted xenograft mice, as in vitro." (PMID 33838671, 2021). "In addition, the argininosuccinate/citrulline ratio, a further readout of ASS1 activity, was markedly higher in cells cultured in DMEM-F12 compared with the tumor or with cells cultured in Plasmax." (PMID 30613774, 2019). "ASS1 is not expressed in many tumor cells and its absence confers a proliferative advantage to these cells." (PMID 30813354, 2019). "TMZ alone and in combination with ADI-PEG20 produced disruption of tumour architecture in ASS negative mice whereas in ASS1 positive mice this feature was only observed in the combined treatment group." (PMID 30546006, 2018). "Prior to BRAFi treatment, low expression of ASS1 can be seen in tumor tissue from patient #4, but not from patient #5." (PMID 29094484, 2017). "The up or down regulation of ASS1 in MPM is quite controversial, many scientists considered MPM an ASS1 lacking tumour, however, others reported an upregulation in this tumour." (PMID 27835874, 2017). "In preclinical studies, it was shown that the combination of arginine deprivation (using ADI-PEG 20) and pemetrexed leads to a potentiation of cytotoxicity in ASS1-negative tumor cells." (PMID 28388291, 2017).
tumor (continued). "It is widely anticipated that arginine deprivation-based therapy is exclusively applicable for ASS1-negative tumor entities as they cannot rely on plasma citrulline for arginine synthesis." (PMID 27689335, 2016). "ASS1 and IRF1 have been reported to act as tumor-suppressors." (PMID 26036313, 2015). "The immunohistochemical staining results were categorized into three groups: ASS1 loss (absence of ASS1 protein expression in tumor cells), low ASS1 expression (less than 10% of tumor cells with ASS1 expression), and positive ASS1 expression (more than 10% of tumor cells ASS1 positive)." (PMID 41300990, 2025). "Importantly, combining arginine-intrinsic (ASS1-KD) and -extrinsic (AFD) deprivation with ruxolitinib gavage treatments in 4T1-bearing mice, starting on day 11 when 4T1 tumors are palpable, significantly reduced tumor size." (PMID 41511309, 2025). "In summary, these results demonstrate that EVO is capable of suppressing the expression of the ASS1 protein via the Wnt/β-catenin/c-MYC signaling pathway, thereby suppressing arginine synthesis metabolism and tumor growth, while also activating the immune microenvironment of tumor cells." (PMID 41304979, 2025). "Therefore, therapeutic arginine deprivation can starve tumor cells to achieve favorable antitumor effects and has become a potential anti-tumor strategy for several tumor types, including ASS1-negative GBM." (PMID 38632627, 2024). "Besides, overexpression of ASL or ASS1 promotes cell proliferation, indicating that TET2-urea cycle-mTORC1 axis may play an important role in tumor growth." (PMID 37550284, 2023). "To determine the relevance of the pro-inflammatory cytokine profile to the tumor cell-macrophage metabolic cooperation, we studied whether the tumor-derived pro-inflammatory cytokines induced by ADI-PEG20 modulated ASS1 and ASL expression in macrophages and tumor cells, respectively." (PMID 37010783, 2023). "One potential avenue for therapeutic development may be found in the observation that around 60% of MPM tumours do not express asparagine synthetase (ASS-1)." (PMID 39516654, 2023). "Furthermore, the therapeutic enzyme, pegylated arginine deiminase (ADI-PEG20; pegargiminase), selectively degrades arginine into citrulline and ammonia and inhibits a wide range of ASS1-negative tumor models in vivo." (PMID 37010783, 2023). "However, some tumor subtypes (such as melanoma, hepatocellular carcinoma, and prostate cancer) cannot synthesize arginine because their ASS1 is not expressed." (PMID 37895948, 2023). "However, without ASS1, tumor cells are unable to synthesize arginine from citrulline and are dependent on exogenous arginine." (PMID 35674458, 2022). "For instance, we recently demonstrated the increase in vivo persistence and efficacy of anti-CD33 CAR-T metabolically enhanced by inserting ASS1 and OTC expression domains such that these cells could re-synthesized arginine from citrulline discarded by the tumor cells." (PMID 34094976, 2021). "However, so far there has been no report on demethylation and subsequent upregulation of ASS1 expression as a mechanism to acquire resistance in tumor cells to ADT." (PMID 34299249, 2021). "We examined HDAC inhibitor panobinostat (PAN) and Arg deprivation in a panel of human PDAC cell lines, in ASS1-high and -knockdown/knockout isogenic models, in both anchorage-dependent and -independent cultures, and in multicellular complex cultures that model the PDAC tumor microenvironment." (PMID 31903153, 2020). "Arginine deprivation treatment strategies are not yet considered for tumor entities, which initially have a detectable amount of ASS1 protein or could induce expression of ASS1 gene upon arginine starvation." (PMID 27689335, 2016).
tumor (continued). "Furthermore, ASS1-methylated cell lines exhibited autophagy and caspase-dependent apoptosis following treatment with ADI-PEG 20, and the autophagy inhibitor chloroquine potentiated the apoptotic effect of ADI-PEG 20 in malignant lymphoid cells and patient-derived tumor cells." (PMID 37445845, 2023). "Indeed, the ASS1 mRNA levels appears to be significantly upregulated in ~ 9% of primary HNSCC and a strong negative correlation between high tumor ASS1 levels and clinical outcome (relapse-free and overall survival) is observed in the HNSCC patient cohort of The Cancer Genome Atlas (TCGA) dataset." (PMID 33230565, 2021). "However, our data indicated that majority of the PDAC patients might not benefit from arginine deprivation treatment as their tumor have sufficient ASS1 protein for endogenous arginine production." (PMID 28187218, 2017). "Conversely, hepatic periportal markers (e.g., ALDOB, HAL, ASS1) and a subset of CYP-related proteins (e.g., CYP2A6, CYP2A7, CYP2B6) were either absent or downregulated in the tumor region." (PMID 39567475, 2024). "In summary, our data implicate a novel macrophage-mediated mechanism of resistance to ADI-PEG20 in ASS1-negative MPM, namely the delivery of argininosuccinate by the macrophage-rich tumor microenvironment under cytokine control." (PMID 37010783, 2023). "At the end of treatment, tumors were harvested and weighed to confirm the synergistic effect of panobinostat and ADI-PEG20 on suppressing ASS1-low, but not ASS1-high, PDAC tumor growth." (PMID 31903153, 2020). "However, almost all therapeutic strategies for the treatment of tumors with low ASS1 expression ignore the tumor suppressor role of ASS16–8,12,13, and there are no tools currently available to reestablish the expression and/or activity of ASS1 in tumor cells." (PMID 33859183, 2021).
infection (10 papers, 2012 to 2025). The state of being infected such as from the introduction of a foreign agent such as serum, vaccine, antigenic substance or organism. "Specifically, the addition of FUC caused a further reduction in mRNA expression levels of NHE2, TRPV6, APOA1, APOA4, APOB, APOC3, and ASS1 compared to PEDV infection alone, while FUC supplementation counteracts PEDV-induced ARG1 upregulation." (PMID 40218394, 2025). "Our results showed that T.mu-colonized mice upregulated intestinal Nos2, Otc, and Ass1 expression, while downregulated Arg1 expression post infection, compared to the C. difficile-infected T.mu-free control mice." (PMID 38565558, 2024). "Arginino Succinate Synthase 1 (ASS1), which catalyzes the rate limiting step in arginine synthesis, was highly expressed throughout infection, including a period from 9 to 24 HPI when expression was approximately double that of the uninfected cells." (PMID 32255806, 2020). "Hepatocytes clustered by the infection status of the mice, and we confirmed hepatocyte-intrinsic repression of Ass1 and Otc upon infection, which inversely correlated with expression levels of the ISG Ifit1 on the single-cell level." (PMID 31784108, 2019). "Transcriptional repression of Otc and Ass1 manifested in reduced abundance of OTC and ASS1 proteins in hepatocytes as observed by immunohistochemistry on days 2 and 8 after infection." (PMID 31784108, 2019).
metabolic disorder (5 papers, 2019 to 2023). "Citrullinemia type I (CTLN1) is a rare congenital metabolic disease (1 in 250,000 live births) caused by mutations in the argininosuccinate synthetase (ASS1) gene." (PMID 36263152, 2022).
lung (4 papers, 2017 to 2023). "Another example is that of argininosuccinate synthetase 1 (ASS1), a rate-limiting enzyme in arginine metabolism that is downregulated in a Thioacetamide (TAA)-induced liver injury model." (PMID 37107704, 2023). "ARG2 may serve as a potential predictive biomarker, in addition to ASS1 and OTC, for PEGylated ARG1 treatment in lung SCC." (PMID 30808864, 2019).
hematological malignancies (1 paper, 2017). "Arginine deprivation is a novel therapeutic modality for several ASS1-deficient, arginine-auxotrophic solid and hematological malignancies." (PMID 28223985, 2017).